EDN1 (endothelin 1)
Diseases named in the same sentence as EDN1 in open-access papers (continued):
Sharing a sentence is not in itself a finding about the gene and the disease.
endothelial dysfunction (continued). "The loss of pericytes and endothelial dysfunction are the hallmarks of these early stages of diabetic microangiopathy, and the balance between nitric oxide (NO) [vasodilator] and endothelin-1 (ET-1) [vasoconstrictor] is essential in determining the hemodynamic response of the capillaries." (PMID 23431285, 2013). "It has been established that the reduced relaxation response to ACh or SNP in SHR, due to endothelial dysfunction, is caused by oxidative stress, decreased production and bioavailability of NO, eNOS uncoupling, and hyper-responsiveness to contracting agents such as angiotensin II and endothelin-1." (PMID 36364149, 2022). "Decreased NO is a manifestation of endothelial dysfunction and is associated with decreased NO synthase activity (competitive inhibition by L-arginine or competitive inhibition by asymmetric dimethylarginine) or decreased NO bioavailability (overexpression of endothelin-1)." (PMID 36405582, 2022). "Although PM2.5 exposure is associated with endothelial dysfunction and the vasoconstrictor peptide endothelin-1 (ET-1) is upregulated in endothelial dysfunction, the effects of PM2.5 on ET-1 and whether or not ET-1 mediates the downstream effects of PM2.5 are unclear." (PMID 32309625, 2019). "Thus, insulin may also cause endothelial dysfunction through increased endothelin-1 availability and through downstream effects on NAD(P)H oxidase and superoxide anion production." (PMID 20334663, 2010). "An imbalance characterized by decreased NO and increased EDN1 contributes to endothelial dysfunction and vascular damage." (PMID 41496209, 2026). "Endothelial dysfunction arises from increased endothelin-1, reduced endothelial nitric oxide synthase (eNOS) activity and lower NO bioavailability, promoting vasoconstriction, hypertension, and left ventricular hypertrophy." (PMID 41212210, 2026). "Endothelin-1 (ET-1), a vasoconstrictive peptide, is an important mediator of neurohormonal activation, endothelial dysfunction, and cardiac remodeling—key processes involved in the pathogenesis of AHF." (PMID 40283182, 2025). "Leptin also enhances endothelial dysfunction by stimulating endothelin-1 production, a potent vasoconstrictor, while simultaneously reducing NO bioavailability through the generation of reactive oxygen species via NADPH oxidase activation." (PMID 41470134, 2025). "Endothelial dysfunction is also manifested by excessive release of vasoconstrictive factors such as endothelin-1 (ET-1)." (PMID 39958826, 2025). "First, IR induces endothelial dysfunction by reducing nitric oxide bioavailability, increasing oxidative stress, and enhancing endothelin-1 activity, thereby impairing vasodilation." (PMID 41458543, 2025). "Endothelin-1 (ET-1) is a potent vasoconstrictor, a mediator of endothelial dysfunction, and a driver of fibrogenesis." (PMID 41010963, 2025). "Serum and CSF biomarkers such as interleukin-6 (IL-6) and endothelin-1 (ET-1) indicate inflammatory and endothelial dysfunction, and they rise days before radiographic or clinical manifestations." (PMID 41194849, 2025). "Markers of endothelial dysfunction include elevated plasma levels of soluble vascular cell adhesion molecule (sVCAM), soluble intercellular adhesion molecule (sICAM), endothelin-1, and E-selectin." (PMID 41156509, 2025). "This leads to endothelial dysfunction and the release of endothelin-1 (ET-1), a potent vasoconstrictor released by endothelial cells." (PMID 41226024, 2025). "Oxidative stress plays an important role in vasospasm by promoting endothelial dysfunction, activating vasoconstrictors such as endothelin-1 (ET-1), and impairing the nitric oxide (NO) vasodilator system." (PMID 40567377, 2025). "These EVs overexpress transcripts for proteins linked to vascular injury, apoptosis, and inflammation, including endothelin-1 (EDN1) and caspase-1 (CASP1), both of which contribute to endothelial dysfunction and heightened cardiovascular risk." (PMID 40725065, 2025).
endothelial dysfunction (continued). "Factors contributing to endothelial dysfunction, such as increased endothelin-1, decreased prostacyclin, and decreased nitric oxide, are observed in COPD and ILD." (PMID 39859549, 2025). "Endothelial dysfunction results in an imbalance between vasoconstrictors (e.g., endothelin-1) and vasodilators (e.g., NO)." (PMID 40217865, 2025). "In the context of obesity, insulin resistance compromises the PI3K/Akt signaling, while enhancing endothelin-1 secretion, leading to a net effect favoring vasoconstriction and endothelial dysfunction." (PMID 41439140, 2025). "One of them is endothelial dysfunction that leads to decreased production of nitric oxide (NO) and increased production of vasoconstrictors, mainly endothelin 1 (ET-1)." (PMID 40548105, 2025). "Endothelin-1 (ET-1) is a potent vasoconstrictor and a key marker of endothelial dysfunction, playing a critical role in cardiovascular homeostasis, inflammation, and organ perfusion." (PMID 40310334, 2025). "Endothelin-1 (ET-1) levels in hospitalized COVID-19 patients were higher during the acute phase of infection, suggesting endothelial dysfunction and a possible role in disease severity and vascular complications." (PMID 40828447, 2025). "Pravastatin has been found to decrease the levels of soluble fms-like tyrosine kinase-1 (sFlt-1) and endothelin-1 (ET-1), two key factors in endothelial dysfunction." (PMID 40786270, 2025). "Endothelial dysfunction triggers vascular damage, immune activation, and the production of endothelin-1 and platelet-derived growth factors." (PMID 40217731, 2025). "Future studies should incorporate functional assessments, such as flow-medicated dilation or endothelin-1, to further elucidate the clinical relevance of endothelial dysfunction in NS." (PMID 40478760, 2025). "Elevated levels of the markers of endothelial dysfunction, including endothelin-1, tissue plasminogen activator, fibronectin, and particularly von Willebrand factor, have been observed in patients with PRES." (PMID 40641529, 2025). "Nebivolol, carvedilol, and celiprolol have been shown to inhibit endothelin-1 (ET-1)-mediated vasoconstriction, a significant contributor to endothelial dysfunction in patients with hypertension." (PMID 39759452, 2024). "Endothelial dysfunction is characterized by increased production of vasoconstrictors, such as endothelin-1, and decreased production of vasodilators, such as nitric oxide (NO), resulting in vasoconstriction and reduced renal blood flow." (PMID 39200211, 2024). "Our study showed a direct correlation between the levels of presepsin and the levels of nitrites and big endothelin-1, which suggests that these biomarkers of endothelial dysfunction depend on the extent of bacterial translocation." (PMID 38396668, 2024). "Frailty has been associated with endothelial dysfunction, as evidenced by the following serum markers: intercellular adhesion molecule 1 (ICAM-1), endothelin 1 (ET-1), von Willebrand factor (vWF), plasma thrombomodulin, and asymmetric dimethylarginine (ADMA)." (PMID 39335518, 2024). "In contrast, the TyG index, a simple and reliable surrogate indicator of insulin resistance, indicates endothelial dysfunction, reduced nitric oxide (NO) bioavailability, and increased endothelin-1 (ET-1) secretion." (PMID 38769356, 2024). "Signaling pathways involving nitric oxide (NO), which is a vasodilator, and endothelin-1 (ET-1), a vasoconstrictor, are altered in endothelial dysfunction." (PMID 38396849, 2024). "In particular, in MetS, alterations in the levels of leptin, resistin, tumor necrosis factor-α (TNF-α), IL-6, angiotensin II, endothelin-1 (ET-1), and adiponectin lead to endothelial dysfunction and vasoconstriction." (PMID 38892574, 2024). "The vascular tone is also affected; endothelial dysfunction often results in decreased nitric oxide (NO) synthesis and the increased release of vasoconstrictors, including endothelin-1 (ET-1) and angiotensin II." (PMID 39408968, 2024).
endothelial dysfunction (continued). "Endothelial dysfunction leads to the upregulation of endothelin-1(ET-1) and this lead to changes in the blood vessel walls such as the formation of thrombosis and plaque." (PMID 38187330, 2024). "Endothelin-1 is a potent vasoconstrictor that has been involved in processes that leads to endothelial dysfunction." (PMID 39125899, 2024). "Retinoic acid stimulated the function of endogenous NO synthase and decreased expression of endothelin-1 in endothelial cells, alleviating endothelial dysfunction." (PMID 39061983, 2024). "At the molecular level, endothelin-1 (ET-1) and sVEGFR1 are associated with SCN; both can augment endothelial dysfunction." (PMID 38891066, 2024). "An imbalance between NO and endothelin-1, which are in opposition, is characteristic of endothelial dysfunction and is significant for the progression of vascular disease." (PMID 39728884, 2024). "Regarding endothelial dysfunction, the two most extensively studied endothelial mediators are nitric oxide (NO) and endothelin-1, ET-1." (PMID 36829907, 2023). "Endothelin-1 plays an important role in CAD pathogenesis via involvement in endothelial dysfunction, inflammation, atherosclerotic plaque formation, myocardial necrosis, arrhythmogenesis and, finally, left ventricular remodeling and fibrosis." (PMID 37760823, 2023). "Endothelin-1 (EDN1)—a 21-amino acid peptide expressed by various cell types—can regulate vasomotor tone and vascular remodeling, and is an important marker of endothelial dysfunction." (PMID 36675322, 2023). "In conclusion, this study shows that at 24 months after acute COVID-19 infection patients experience a high prevalence of PCC symptoms which correlate with inflammatory cytokine IL-1Ra and markers of endothelial dysfunction, especially endothelin-1." (PMID 37868959, 2023). "This process is also facilitated by CH-induced endothelial dysfunction, which involves the increased production of vasoconstrictor and proliferative factors such as endothelin 1 (ET-1)." (PMID 38136180, 2023). "Mechanistically, endothelial dysfunction results in increased production of vasoconstrictors such as endothelin-1 (ET-1)." (PMID 36830749, 2023). "Among several biomarkers, endothelin-1 (ET-1) seems to be involved in many facets of the pathogenesis of acute HF including neurohormonal activation, endothelial dysfunction, cardiac remodeling, inflammation, atherosclerosis and altered renal function." (PMID 37895150, 2023). "Endothelial dysfunction and a reduced contractile response to endothelin-1 trigger vasoconstriction have been previously proposed as important factors contributing to vascular stiffness." (PMID 37268640, 2023). "Endothelin 1 (ET-1) is involved in the pathogenesis of endothelial dysfunction and PF in the rodent PF model, and inhibition of its receptors can retard PF." (PMID 37240093, 2023). "Endothelial dysfunction and nNOS uncoupling support pathomechanism 2 in e-cigarette vapor-exposed mice and sympathovagal activation, and increased endothelin-1 expression and blockade by macitentan points toward pathomechanism 3 in vaping healthy subjects." (PMID 37084087, 2023). "Endothelin-1 can induce endothelial dysfunction via the inhibition of NO pathway activity, increases in oxidative stress and inflammation and the dysregulation of glucose and lipid metabolism." (PMID 37760823, 2023). "It exerts a pivotal role in endothelial dysfunction by increasing the synthesis and release of vasoconstrictor factors like endothelin-1 and reducing those of vasodilator factors such as nitric oxide." (PMID 37686034, 2023). "We also observed increased expression of the potent vasoactive peptide endothelin-1 (EDN1) as well as oxidized low-density lipoprotein receptor-1 (OLR1), which is a key molecule associated with endothelial dysfunction during atherosclerosis progression." (PMID 37845224, 2023).
endothelial dysfunction (continued). "Endothelial dysfunction is characterized by the enhancement of endothelin-1 (ET-1) expression and the reduced expression of eNOS in endothelial cells." (PMID 37367894, 2023). "Endothelin-1 (ET-1) and nitric oxide (NO) regulate endothelial function so alterations in their normal effects leads to endothelial dysfunction with the progression of vascular disease." (PMID 36829843, 2023). "Multiple correlations were found between several PCC symptoms and markers of endothelial dysfunction (endothelin-1 and von Willebrand factor) and systemic inflammation (Interleukin-1 Receptor antagonist)." (PMID 37868959, 2023). "Endothelin-1 (ET-1) is a potent vasoconstrictor that contributes to endothelial dysfunction, however, its abundance and actions in GDM are unclear." (PMID 37893034, 2023). "Oxidative stress can aggravate endothelial dysfunction, characterized by an increase in the synthesis and release of endothelium-derived contraction factors (such as endothelin 1 and ET-1) and a decrease in diastolic factors (such as NO)." (PMID 35744848, 2022). "Consistent with this, L-NAME administration did not alter mesenteric artery expression of the enzyme responsible for production of nitric oxide Nos3, the endothelial dysfunction marker Vcam-1, or the receptors for vasoconstrictor endothelin-1, Ednra and Ednrb." (PMID 36260752, 2022). "A well-known marker of endothelial dysfunction is reduced production of vasodilators (e.g., nitric oxide and prostaglandins) in lieu of vasoconstrictive factors (e.g., thromboxane A2 and endothelin 1)." (PMID 36403044, 2022). "Chronic inflammation and hypoxia, endothelial dysfunction, an increase in endothelin-1 expression, a decrease in nitric oxide levels and upregulation of neurohormones can be shown as the causes of these changes." (PMID 36013595, 2022). "Over stimulation of AT1R and ET-1R vascular receptors by angiotensin II (AngII) and endothelin-1 (ET-1), respectively, lead to sustained vasoconstriction and hence blood pressure elevation and endothelial dysfunction." (PMID 35884947, 2022). "Endothelin-1 (ET-1) is another potent vasoconstrictive molecule that is known to be elevated in PE and contribute to endothelial dysfunction in multiple cardiovascular diseases." (PMID 36359910, 2022). "Endothelin-1 (ET-1) is another participant in the development and progression of endothelial dysfunction." (PMID 35330470, 2022). "Tb-4 improves endothelial dysfunction through enhancing hiPSC-EC viability, reducing senescence and endothelin-1 production, and improves angiogenic potency in diabetes." (PMID 35012642, 2022). "In other words, endothelial dysfunction and damage is followed by endothelial expression of prothrombotic molecules and receptors, such as P-selectins, angiopoietin-2 and endothelin-1, which actively contribute to thrombosis." (PMID 36295093, 2022). "The analysis of differentially expressed genes showed that some genes associated with endothelial dysfunction were significantly upregulated, such as CD36, EDN1, ANGPT2 and so on." (PMID 36091033, 2022). "Endothelial dysfunction can be measured by its serum markers such as endothelin-1, vascular adhesion molecule, and intercellular adhesion molecule." (PMID 35773726, 2022). "The increased levels of cytokines together with overproduction of endothelin 1 (ET-1), a potent vasoconstrictor and a marker of endothelial dysfunction, correlate with the clinical severity of CTEPH." (PMID 35563797, 2022). "Nitric oxide (NO) and endothelin-1 (ET-1) are natural counterparts in vascular function, and an imbalance between these two mediators is a characteristic of endothelial dysfunction and is important in the progression of PE." (PMID 35213910, 2022). "In vitro studies demonstrated that in addition to its vasoregulatory properties, endothelin-1 stimulates the release of endothelial cell-derived microvesicles, which can then induce endothelial dysfunction." (PMID 36230894, 2022).
endothelial dysfunction (continued). "Such biomarkers of endothelial dysfunction include endothelin-1 (ET-1), circulating endothelial cells, endothelial microparticles, endoglin, etc., plasma soluble intercellular adhesion molecules (siCAM), or high-sensitive C-reactive particles (hs-CRP)." (PMID 35008732, 2021). "In diabetes, EdnRA in GECs is activated by increased circulating Edn-1 or local Edn-1, resulting in mitochondrial stress and endothelial dysfunction." (PMID 34485320, 2021). "There are substantial clinical evidence for increased plasma endothelin-1 (ET-1) levels in patients with diabetes mellitus, leading to endothelial dysfunction." (PMID 34909290, 2021). "Endothelial dysfunction (ED), characterized by impaired nitric oxide (NO) release and increased endothelin-1 (ET-1) release, is fundamental in the early stage of CVD." (PMID 34531738, 2021). "The physiological imbalance between NO and endothelin-1 molecules represents endothelial dysfunction." (PMID 34206463, 2021). "The reduced bioavailability of NO induces the production and release of endothelium-derived vasoconstrictor prostanoids and endothelin-1, leading to vasoconstriction which amplifies the degree of endothelial dysfunction." (PMID 33623633, 2021). "The cytokine surge contributes to endothelial dysfunction via uncoupled nitrous oxide (eNOS), increased endothelin-1(ET-1) levels, reactive thrombocytosis, and formation of emboli which lodge into pulmonary vessels causing acute hypoxic changes." (PMID 34457265, 2021). "Reduced NO production and increased production of vasoconstrictor, such as endothelin-1, are typical phenotypes of endothelial dysfunction." (PMID 34136485, 2021). "An important feature of endothelial dysfunction is an increased production and biological activity of the potent vasoconstrictor and proinflammatory peptide endothelin-1 (ET-1)." (PMID 34156537, 2021). "Endothelial dysfunction is known to occur due to decreases in NO bioavailability and increases in endothelin-1 (ET-1), angiotensin II, and oxidant levels, which contribute to an imbalance in endothelium-derived relaxing and constricting factors." (PMID 33886808, 2021). "Among other actions, AVP also stimulates secretion of endothelin-1 (ET-1) from endothelial cells which enhances endothelial dysfunction and coagulation disorders as well as increases cellular sodium-dependent phosphate transport via Pit1 and Pit2." (PMID 32033584, 2020). "Endothelin-1 (ET-1) has a relevant impact on the development of endothelial dysfunction, as it elicits vasoconstriction and several deleterious effects including chemotactic and mitogenic properties, which culminates in smooth muscle cells proliferation." (PMID 32455866, 2020). "Flow-mediated dilation was measured together with the assessment of the values of endothelin-1, von Willebrand factor, and asymmetric dimethylarginine to identify endothelial dysfunction." (PMID 33118727, 2020). "Among HIV proteins, glycoprotein 120 (gp120) enhances endothelin-1 release from endothelium, while Nef and transactivator of transcription (Tat) contribute to endothelial dysfunction and inflammation." (PMID 33143256, 2020). "Several studies have found that the imbalance between endothelin-1 and nitric oxide in patients with CSF supports the involvement of endothelial dysfunction in CSF etiopathogenesis." (PMID 32460702, 2020). "These patients showed a reduced response to acetylcholine, a marker of endothelial dysfunction and enhanced vasoconstrictor response to U46619, which is a thromboxane and endothelin-1 agonist." (PMID 33143256, 2020). "Endothelial dysfunction was assessed on admission by quantifying reactive hyperemia-peripheral arterial tonometry and plasma levels of endothelin-1, soluble E-selectin, endocan and syndecan-1." (PMID 33053025, 2020).